TLR4 (toll like receptor 4)
Diseases named in the same sentence as TLR4 in open-access papers (continued):
Sharing a sentence is not in itself a finding about the gene and the disease.
injury (continued). "Because TREM-1 is reported to amplify the inflammatory response initiated by TLR engagement, we further investigated whether TLR4 signaling was inhibited by MH in acute liver injury." (PMID 31616301, 2019). "Therefore, in the present work, the analysis of AP-1 expression in TLR4-MAPKs signal pathway will easily understand the protective effect of maltol on CCl4 induced liver injury." (PMID 30142916, 2018). "In addition, we have demonstrated that WISP1 interacts with TLR4 by co-immunoprecipitation and mediates ventilator-induced lung injury (VILI) dependent on TLR4 signaling." (PMID 30522479, 2018). "Previous studies showed that the TLR4 pathway plays a role in ischemic brain injury, brain trauma, CNS infection, neurodegenerative disease, and brain autoimmune inflammation, whereas only a preliminary understanding of the role of TLR4 in epileptogenesis has been obtained in recent years." (PMID 29382328, 2018). "In this study, LPS upregulated expression of NF-κB and its upstream proteins (TLR4 and Myd88), while indirubin markedly alleviated NF-κB activation, which might serve as the protective mechanism in LPS-induced acute lung injury." (PMID 28525368, 2017). "Meanwhile, indirubin markedly inhibited TLR4 and NF-κB signals, which might further mediate the oxidative stress and inflammation in the LPS-induced acute lung injury." (PMID 28525368, 2017). "Moreover, interventions in the pathogenesis of the TLR4/NF-κB pathway showed its potential as a therapeutic target in acute alcohol-induced liver injury." (PMID 28891983, 2017). "TLR4 signaling has been implicated in O3-mediated lung inflammation through interaction with hyaluronan fragments, and both infection-induced and acid-induced acute lung injury also appear to be triggered by TLR4 but through interaction with oxidized phospholipids generated from oxidative stress." (PMID 26410792, 2015). "LycogenTM (an extract of R. sphaeroides) might contribute to the reduction of the immune response in cisplatin-induced kidney injury by inhibiting TLR4 signaling." (PMID 24335753, 2013). "Ethanol administration can also lead to the synthesis of Toll-like receptor 4 (TLR4) protein and its gene expression in Kupffer cells, indicating that TLR4 may play a major role in the development of alcohol-induced liver injury." (PMID 22991573, 2012). "Moreover, TLR4-dependent activation of NKCC1 can also regulate activation of TRPV4 in cerebral edema in a model of traumatic brain injury, which suggests that there may be additional overlapping mechanisms of regulation between NKCC1 and TLR4." (PMID 36639792, 2023). "In addition, TLR4 has been found to have a pivotal role in the progression of acute liver injury." (PMID 28197212, 2017). "Furthermore, a critical role of TLR4 was demonstrated by our observations that brain water content, neurological deficit score and neuronal death were significantly decreased in TLR4-/- mice in comparison to WT mice suffering a similar severity of head trauma." (PMID 24669820, 2014). "Targeting of the key necroptosis regulator RIPK1 or TLR4, which is known to be an inducer of the necroptosis pathway upstream of RIPK1, protects against hyperammonemia-induced liver injury and reduces circulating ammonia levels." (PMID 40053595, 2025). "In blunt chest trauma and hemorrhagic shock-induced acute lung injury, PHC plays a crucial role in preventing TLR4 signaling and inflammation." (PMID 38671448, 2024). "•In-depth analysis of TLR4/NF-κB p65 and CYP2E1/ROS/Nrf2 pathways expands insights, guiding precise therapies for alcohol-induced liver injury." (PMID 37868808, 2023). "The expression levels of TLR4, NF-κB, PI3K, and Akt were compared between the control group and the acute lung-injury (ALI) group." (PMID 37175637, 2023). "In rats with traumatic brain injury, DEX alleviates the early neuronal damage via suppression of inflammation through the TLR4/NF-κB pathway." (PMID 36273189, 2022).
injury (continued). "Interestingly, although few studies have assessed whether CC16 exerts its effect on cells through binding to a receptor, a study of lipopolysaccharide-induced acute lung injury indicated that CC16 suppressed TLR4 expression levels on lung macrophages, which was similar to our observations." (PMID 33541260, 2021). "High-mobility group box-1 (HMGB1) protein, a member of the high-mobility group 1 (HMG-1) family, modulates cell death in acute liver injury by NF-κB signal pathway activated by advanced glycan end products (RAGE) and toll-like receptor 4 (TLR4)." (PMID 34366845, 2021). "In conclusion, these data revealed that MF exhibited significant protection against LPS/D-GalN-induced acute liver injury and alleviated TNF-α production through the inhibition of the TLR4/NF-κB signaling pathway." (PMID 32158448, 2020). "Interestingly, PACAP could inhibit TLR-4 activation in a model of traumatic brain injury." (PMID 30967875, 2019). "Similar mechanisms of magnolol can also be found in LPS-induced acute lung injury mice models by inhibiting the tumor necrosis factor-alpha (TNF-α), IL-1β, phosphorylation of IκB-α and NF-κB, and expression of toll-like receptor 4 (TLR4)." (PMID 28726741, 2017). "Similarly, the reduced expression of hepatic IκB by GalN/LPS injection was also reversed by 200 mg/kg cordycepin, implying that cordycepin might exert its anti-inflammatory effect via decreasing TLR4 expression and inhibiting NFκB activation in GalN/LPS-induced acute liver injury." (PMID 28522898, 2017). "The current study supports an interaction between TLR4 and IRAK-3 signaling pathway for the over-expression and release of pro-inflammatory cytokines during ventilator-induced lung injury." (PMID 20199666, 2010). "In ischemic renal injury, NET-derived components such as cf-DNA and high-mobility group box 1 initiate NOD-like receptor family pyrin domain containing 3 (NLRP3) inflammasome assembly via Toll-like receptor 4 (TLR4) signaling." (PMID 41244813, 2025). "It is interesting to note here that a similar modulation of NOD2 signaling by extracellular HMGB1, not cytosolic HMGB1, has been reported in an animal model of acute lung injury, wherein extracellular HMGB1/TLR4 signaling activates NOD2, which induces autophagy and suppresses NOD2-RIP2 signaling." (PMID 35954253, 2022). "This may partially explain the potential material basis of JDNW ameliorating ACLF liver injury by reducing oxidative stress and apoptosis by inhibiting the HMGB1/TLR-4/NF-κB pathway." (PMID 35873636, 2022). "PMN from trauma patients show reduced expression of CD16, TLR2, and TLR4." (PMID 34520397, 2021). "Based on previous studies, TLR4 activation has great significance in Gram-negative sepsis-induced kidney injury, and TLR4 can activate the NKT cell which is a dominant IFN-γ production immune cell." (PMID 30915370, 2019). "This interaction of TLR4 and MyD88 triggers the downstream signaling cascade leading to the activation of the nuclear factor κB (NF-κB) pathway, further releasing inflammatory cytokines such as TNF-α and IL-6, which, in turn, can result in liver injury." (PMID 25328713, 2014). "To test this hypothesis, we used pharmacologic and genetic manipulations of TLR4 and its downstream signaling pathways to define the cell-specific and signaling pathway effects of TLR4 in vitro and in a murine model of CFH-induced acute lung injury." (PMID 37991487, 2024). "In conclusion, the findings decode a previously unidentified role for a myeloid‐TLR4 dependent Nr4a1/Ear2 negative feedback mechanism in macrophage‐mediated progressive renal injury, implying that activation of Nr4a1‐Ear2 axis can be a novel and effective immunotherapy for anti‐GBM cGN." (PMID 35484716, 2022). "miR-30b could regulate interleukin-10 and toll-like receptor 4 expressions in T-lymphocytes, may participate in NLRP3 inflammasome expression in chronic liver injury and be involved in the inflammatory response of acute lung injury in children." (PMID 34571708, 2021).
injury (continued). "Thus, several publications revealed a contribution of TLR2 or TLR4 in non-infectious acute lung injury (ALI), acute respiratory distress syndrome (ARDS), chronic obstructive pulmonary disease (COPD), cystic fibrosis and asthma." (PMID 28836991, 2017). "We have demonstrated that ethanol is capable of activating TLR4/IL-1RI receptors in astroglial and microglial cells to trigger TLR4 signaling and to produce cytokines induction (IL-1β, TNF-α, IL-6) and inflammatory mediators (iNOS, COX-2), which can lead to neuroinflammation and brain injury." (PMID 25136295, 2014).
Hepatic steatosis (123 papers, 2010 to 2026). Steatosis is a term used to denote lipid accumulation within hepatocytes. "TLR4 is an LPS receptor and elevation of LPS in most animal models of NAFLD causes hepatic steatosis, hepatic insulin resistance, and increased liver weight, making TLR4-LPS the key pathway promoting the development of NAFLD." (PMID 40076851, 2025). "Recent studies show that gut dysbiosis—more especially, an enhanced Firmicutes/Bacteroidetes ratio—helps to cause hepatic steatosis using increased lipopolysaccharide translocation and TLR4-mediated inflammatory pathways." (PMID 40868109, 2025). "The expression of TLR4 increased in hepatic steatosis individuals and is associated with raising serum LPS levels and intestinal barrier disruption, suggesting that the LPS/TLR4 pathway is one of the major mechanisms acting on the gut–liver axis." (PMID 36771448, 2023). "The pathogenetic role of microbe-derived metabolites is well established in animal model studies, showing that hepatic steatosis, inflammation and fibrosis are attenuated in TLR-4- and TLR-9-deficient mice on a high-fat or choline-deficient diet." (PMID 36986052, 2023). "Abnormal translocated LPS derived from gut pathogenic bacteria binds to TLR4 of Mψs to activate the transcription factor NF-κB that is responsible for inflammatory cytokine synthesis, finally leading to liver injury and hepatic steatosis." (PMID 33390939, 2020). "More importantly, sCD163, microbial translocation, and Toll-like receptor 4 signaling have been associated with fatty liver progression to NASH and fibrosis." (PMID 28929125, 2017). "Different animal models reveal that inflammasome deficiency-associated changes in the gut microbiota composition were associated with exacerbated hepatic steatosis and inflammation through the influx of TLR4 and TLR9 agonists into the portal circulation." (PMID 26090468, 2015). "Progression of NAFLD to NASH occurs in a subset of patients with fatty liver disease, and this progression is largely linked to the activation of toll like receptor 4 (TLR4) by both exogenous and endogenous ligands." (PMID 25657646, 2014). "Additionally, TLR4 has been linked to inflammatory activation in the livers of obese patients, contributing to the development of hepatic steatosis, steatohepatitis, and IR." (PMID 40722894, 2025). "TLR4 deficiency also protected mice from methionine choline-deficient diet-induced liver fat deposition and hepatocyte-specific TLR4 knockout ameliorated hepatic steatosis in the HFD-fed mice." (PMID 34205789, 2021). "Indeed, a detrimental role for TLR4 in NAFLD is supported by the finding that TLR4 deficiency protected mice from HFD-induced hepatic steatosis and inflammation." (PMID 34943809, 2021). "Present studies have shown that TLR4 was associated with hepatic steatosis and NAFLD." (PMID 33708118, 2020). "Besides, previous studies have shown that mutant TLR4 mice, or mice deficient in TLR4, display a lower probability of alcohol-induced fatty liver disease." (PMID 33149748, 2020). "Recent data has shown that TLR4 is also implicated in hepatic steatosis and NAFLD pathogenesis." (PMID 31788011, 2019). "Recent reports have suggested that PNPLA3, IL28B and TLR4-associated single nucleotide polymorphisms (SNPs) may have an impact on hepatic steatosis or fibrosis in patients with chronic HCV infection." (PMID 24349054, 2013). "Therefore, regulating antioxidant systems and inflammation through the TLR-4/NF-κB pathway may be an essential strategy to prevent the development of NASH caused by hepatic steatosis." (PMID 39947694, 2025). "Moreover, in a mice model of hepatic steatosis, changes in gut microbiota are associated with exacerbated hepatic steatosis and inflammation through portal influx of TLR4 and TLR9 agonists, leading to enhanced hepatic tumor-necrosis factor (TNF)-α expression that drives NASH progression." (PMID 36986052, 2023).
Hepatic steatosis (continued). "The results demonstrated that chlorogenic acid alleviated hepatic steatosis and inflammation and inhibited the hepatic TLR4 inflammatory pathway." (PMID 41514305, 2026). "Cell and animal studies indicate that gypenosides can effectively attenuate hepatic steatosis associated with MAFLD by concomitantly activating AMPK signaling and inhibiting the TLR4/NF-κB inflammatory pathway." (PMID 41514305, 2026). "In two published studies, it was shown that TLR4 mediated the proinflammatory activity of Saa in mice, and such activities were diminished in Tlr4 knockout mice in studies of periodontal inflammation and hepatic steatosis." (PMID 39940756, 2025). "Numerous studies have reported the effects of various interventions on fatty liver improvement, and research on the mechanisms by which TLR-4/TGF-β1 modulates alcohol-induced hepatotoxicity has also been conducted." (PMID 40077563, 2025). "Dysbiosis-induced activation of the toll-like receptor 4 (TLR4) pathway has also been shown to exacerbate hepatic steatosis and fibrosis." (PMID 41010918, 2025). "In fatty liver diseases, they amplify Toll-like receptor 4 signaling in macrophages and recruit CD8+ T cells." (PMID 40831950, 2025). "The activation of TLR4 by LPS not only fosters insulin resistance but also contributes to hepatic steatosis (fatty liver disease)." (PMID 41303363, 2025). "Our study aims to examine the connection between the plasma levels of IL-17A/F and TLR4 and the extent of hepatic steatosis, as well as the likelihood of fibrosis in patients with MASLD." (PMID 39335657, 2024). "A beneficial effect of OLE was also observed in the liver compartment, as indicated by a significant reduction in liver inflammation, liver steatosis, and fibrosis along with lowered LPS intrahepatic localization and TLR4 macrophage expression." (PMID 38891768, 2024). "Further, LPS challenge in hepatic steatosis models potentiated TLR4/NFκB signaling, leading to accelerated pericellular fibrosis in lipid-laden hepatocytes." (PMID 39796579, 2024). "In alcohol-fed rats, scopoletin regulates AMPK and the toll-like receptor 4 (TLR4)/myeloid differentiation major response gene 88 (MyD88)/NF-κB pathway and alleviates alcoholic hepatic steatosis and inflammation." (PMID 38464713, 2024). "Lactobacillus casei Shirota was found to prevent fructose-induced liver steatosis through the hepatic TLR4 signaling cascade." (PMID 38018983, 2024). "Lastly, Galectin-3 is thought to promote hepatic inflammation in fatty liver disease via TLR-4-mediated NLRP3 inflammasome activation." (PMID 39635525, 2024). "The continuous activation of TLR4 in this pro-inflammatory setting accelerates the transition from benign fatty liver disease to more severe forms like steatohepatitis, which is strongly associated with HCC." (PMID 39335657, 2024). "Saa1 establishes a regulatory circuit involving Saa1/TLR4/NF-κB/Saa1 feedback, which serves as a trigger for the development of liver steatosis and the intrahepatic inflammatory response." (PMID 38068762, 2023). "The improved function of the intestinal barrier prevents the entry of endotoxins into the liver, thus inhibiting the expression of the TLR4/NF-κB pathway, mitigating inflammation and the resulting hepatic steatosis." (PMID 38004120, 2023). "As a consequence, it maintains the intestinal barrier integrity, reduces the translocation of intestinal-derived LPS, and inhibits the liver LPS/TLR4 signaling pathway to improve hepatic steatosis and steatohepatitis." (PMID 36771448, 2023). "LPS binds to Toll-like receptor 4 on the surface of hepatic Kupffer cells and activates the NF-κB-mediated TNF-α signaling pathway, causing hepatic steatosis and inflammation." (PMID 38126998, 2023). "Deletion of NLRP6 alters the configuration of the intestinal microbiota, resulting in hepatic steatosis and inflammation via TLR4 signaling." (PMID 37664266, 2023).